RNU6-951P (RNA, U6 small nuclear 951, pseudogene)
Gene: Small nuclear RNA gene on chromosome 2 (38,147,415 to 38,147,521, forward strand). Ensembl gene ENSG00000199603.
Homologues: Orthologues: chimpanzee U6 (99% identical), macaque U6 (88% identical), pig U6 (82% identical), rat U6 (79% identical). Paralogues in human: RNU6-10P (87% identical), RNU6-38P (87% identical), RNU6-921P (87% identical), RNU6-1 (86% identical), RNU6-1103P (86% identical), RNU6-15P (86% identical), RNU6-2 (86% identical), RNU6-20P (86% identical), RNU6-3P (86% identical), RNU6-4P (86% identical), RNU6-5P (86% identical), RNU6-639P (86% identical), and 1287 more.